COLQ (collagen like tail subunit of asymmetric acetylcholinesterase)
Description:
Anchors the catalytic subunits of asymmetric AChE to the synaptic basal membrane, and is therefore involved in the down-regulation of colinergic synaptic transmission.
Synonyms: EAD; CMS5
Tractability: Antibody: its Gene Ontology location is reachable by antibodies, with high confidence; UniProt predicts a signal peptide or a membrane-spanning region; the Human Protein Atlas places it where antibodies can reach. PROTAC: ubiquitination databases record sites on it.
Gene: Protein-coding gene on chromosome 3 (15,450,132 to 15,521,928, reverse strand). Ensembl gene ENSG00000206561.
Subcellular location: Synapse
Subcellular location (Human Protein Atlas): Plasma membrane; Cell Junctions; Predicted to be secreted
Gene Ontology:
Molecular function: molecular adaptor activity; protein binding; extracellular matrix structural constituent; heparin binding
Biological process: negative regulation of synaptic transmission, cholinergic; protein localization to synapse; acetylcholine catabolic process in synaptic cleft; extracellular matrix organization
Cellular component: extracellular matrix; neuromuscular junction; synapse; basement membrane; extracellular region; synaptic cleft
Genetic constraint (gnomAD): Loss-of-function variants: 48 observed, 67.69 expected, observed/expected ratio (o/e) 0.71, 90% interval 0.56 to 0.9. The upper end of that interval is the gene's LOEUF score, 0.9, which puts it in group 3 of 6, group 1 being the genes least tolerant of losing a copy. Missense variants: 618 observed, 606.61 expected, observed/expected ratio (o/e) 1.02, 90% interval 0.95 to 1.09. Synonymous variants: 217 observed, 216.68 expected, observed/expected ratio (o/e) 1, 90% interval 0.9 to 1.12.
Homologues: Orthologues: chimpanzee COLQ (99% identical), pig COLQ (92% identical), rabbit COLQ (92% identical), mouse Colq (91% identical), rat Colq (90% identical), guinea pig COLQ (85% identical), zebrafish colq (55% identical), zebrafish wu:fc38h03 (47% identical). Paralogues in human: COL22A1 (37% identical), COL11A1 (32% identical), COL5A1 (32% identical), COL11A2 (31% identical), COL4A5 (29% identical), COL2A1 (29% identical), COL4A6 (29% identical), COL4A2 (29% identical), COL5A3 (29% identical), COL1A1 (29% identical), COL4A1 (29% identical), COL5A2 (28% identical), and 25 more.
Diseases named in the same sentence as COLQ in open-access papers:
COLQ is named in the same sentence as 32 diseases in open-access papers, as found by Europe PMC text mining. Sharing a sentence is not in itself a finding about the gene and the disease. The quoted sentences say what the papers report.
congenital myasthenic syndrome (23 papers, 2015 to 2025). Congenital myasthenic syndrome (CMS) is a group of genetic disorders of impaired neuromuscular transmission at the motor endplate characterized by fatigable muscle weakness. "Previous studies have confirmed that pathogenic mutations in the COLQ gene are a known cause of congenital myasthenic syndrome related to acetylcholinesterase deficiency (CMS-EAD)." (PMID 40941413, 2025). "COLQ mutations are associated with congenital myasthenic syndromes (CMS) with 2 case reports of associated PH." (PMID 41222740, 2025). "Surprisingly, ES identified a homozygous splice-site c.393+1G>A variant in COLQ, which is known to cause congenital myasthenic syndrome (OMIM#603034)." (PMID 36697461, 2023). "Patients carrying ColQ mutations and mice deficient for ColQ present with congenital myasthenic syndromes, a class of pathologies characterized by fatigable muscle weakness, with AChE deficiency." (PMID 37356721, 2023). "Studies have shown that mutations in COLQ can lead to congenital myasthenic syndrome (CMS), which causes cardiac autonomic dysfunction." (PMID 37063972, 2023). "To date, over 50 mutations have been identified in the human COLQ gene, all of which leading to a congenital myasthenic syndrome (CMS) with endplate AChE deficiency." (PMID 33362463, 2020). "So far, no mutation has been identified in the ACHE human gene but over 50 different mutations in the COLQ gene are causative for a congenital myasthenic syndrome (CMS) with AChE deficiency." (PMID 33362463, 2020). "Here we report the identification of a missense recessive mutation in COLQ leading to impaired clustering of AchE, suggesting that the Sphynx and Devon Rex neuromuscular disease is a congenital myasthenic syndrome, the first one described in cats." (PMID 26327126, 2015). "Mutations in COLQ are known to cause congenital myasthenic syndromes across species." (PMID 40941413, 2025). "However, in cases with DOK7 and COLQ mutations and slow-channel congenital myasthenic syndrome, symptoms worsen due to pyridostigmine treatment." (PMID 37766777, 2023). "Thus, our study provides new insights into the signaling pathways that are regulated by ColQ-deficiency and highlights for the first time a role for HuR and p38 in mRNA stability in a model of congenital myasthenic syndrome." (PMID 33362463, 2020). "In congenital myasthenia those with CHAT or RAPSYN mutations tend to develop apnoeas but only require NIV during acute exacerbations whereas in other mutations e.g. patients with COLQ may develop nocturnal hypoventilation and require long term home NIV." (PMID 25933065, 2015). "The antagonistic regulation of SRSF1 and hnRNP for COLQ exon 16 was part of pathological processes of congenital myasthenic syndrome." (PMID 38922778, 2024). "It would also be of interest to evaluate whether ColQ or LRP4 identified mutations or autoantibodies, responsible for congenital myasthenia or myasthenia gravis, disrupt or diminish the interaction between LRP4 and ColQ." (PMID 37356721, 2023). "Finally, it should be considered that, in ColQ-mutated congenital myasthenic syndromes, the absence of ColQ may also affect signaling pathways at the NMJ by indirect mechanisms, in addition to its direct modulation of the MuSK–LRP4 complex." (PMID 37356721, 2023).
diverticulitis (3 papers, 2017 to 2024). An infection that develops in the diverticula of the intestinal tract. "GWAS on the Icelandic, Denmark and UK populations replicated gene variants in ARHGAP15, COLQ and FAM155A with increased association with diverticulitis over diverticulosis." (PMID 38831715, 2024). "We have found common sequence variants in introns of the ARHGAP15, COLQ and FAM155A that associate with risk of diverticular disease or diverticulitis." (PMID 28585551, 2017). "We tested the association of diverticulitis versus uncomplicated diverticular disease for variants at the ARHGAP15, COLQ and FAM155A loci." (PMID 28585551, 2017). "Four replicated loci, ARHGAP15, COLQ, FAM155A and TNFSF15, are highlighted to have a stronger association with diverticulitis and may have a role in inflammation." (PMID 38831715, 2024). "We find association of three intronic variants in the genes ARHGAP15 (Rho GTPase-activating protein 15) and COLQ (collagen-like tail subunit of asymmetric acetylcholinesterase) with diverticular disease and in FAM155A (family with sequence similarity 155A) with diverticulitis." (PMID 28585551, 2017).
ptosis (3 papers, 2022 to 2025). The drooping of the upper eyelid. "Notably, all three patients with infantile-onset COLQ mutations experienced recurrent respiratory failure prior to developing obvious ptosis and ophthalmoplegia." (PMID 40494860, 2025). "Interestingly, a grandmother and a father of two siblings with COLQ-CMS carried a heterozygous truncation variant of COLQ, and showed congenital ptosis." (PMID 36835142, 2023). "Although the presence of a pathogenic variant on another allele could not be excluded, a heterozygous variant of COLQ might have caused ptosis." (PMID 36835142, 2023). "Although pathogenic variants in COLQ usually cause severe early onset axial weakness with sparing of EOMs, some cases may have later onset, milder disease with variable occurrence of ophthalmoplegia and ptosis; these patients do not respond to cholinesterase inhibitors." (PMID 35280301, 2022).
diverticular disease (2 papers, 2017 to 2020). A complex disorder characterised by mucosal outpouchings (diverticulae) of the colonic wall which can become infected and inflamed leading to diverticulitis, perforation and bleeding. "We found one rare missense variant rs146687198-G (p.Gly246Ala, MAF=0.22%) in COLQ with large effect on diverticular disease in Iceland (OR=2.06, 95% confidence interval (CI): 1.4, 3.0, P=3.5 × 10−4)." (PMID 28585551, 2017). "Although the association of this rare missense variant with diverticular disease is not of genome-wide significance, the prior probability established by the association of rs7609897-T suggests that the association of rs146687198-G may be real and points to COLQ as the causative gene at this locus." (PMID 28585551, 2017). "None of the diverticular disease variants affect the expression of ARGHAP15, COLQ or FAM155A or of nearby genes, neither in deCODE's RNAseq data on blood and adipocytes nor in data from the various tissues of the GTEx database." (PMID 28585551, 2017).
myasthenia (2 papers, 2021 to 2023). "In addition to myasthenia, COLQ-/- mice exhibit an atrophic phenotype, with fast muscles being more affected than slow muscles." (PMID 34912755, 2021).
myasthenia gravis (2 papers, 2020 to 2023). Myasthenia gravis (MG) is a rare, clinically heterogeneous, autoimmune disorder of the neuromuscular junction characterized by fatigable weakness of voluntary muscles. "Other studies using other myasthenic models also showed increased post-synaptic areas, i.e. in a MuSK myasthenia gravis mouse model, a slow channel model and recently in an AChR-deficient and ColQ-deficient mouse model." (PMID 32543656, 2020).
Respiratory insufficiency (2 papers, 2022 to 2024). "The patient had respiratory insufficiency, which is not commonly seen in the GFPT1 mutation; it is usually associated with mutations of RAPSYN, COLQ, MUSK, and others." (PMID 39559672, 2024).
scoliosis (2 papers, 2023 to 2024). A congenital or acquired spinal deformity characterized by lateral curvature of the spine. "Finally, scoliosis itself is typically associated with mutations of the COLQ, VAMP1, and CHRNE (slow channel syndrome) genes rather than GFPT1 mutations." (PMID 39559672, 2024).
Atrophy (1 paper, 2019). Any weakening or degeneration, especially through lack of use. "The ColQ−/− mouse exhibits features of muscle atrophy, with reduction in type I and increase in type IIA fibres as well as reduced fibre size." (PMID 31220253, 2019).
lymphedema (1 paper, 2021). Excess fluid collection in tissues, causing swelling. "Other receptors with a collagen-like stretch, COLQ and CCBE1, explain muscle weakness and lymphedema." (PMID 33917579, 2021).
microcephaly (1 paper, 2019). A congenital or acquired developmental disorder in which the circumference of the head is smaller than normal for the person's age and sex. "In a Saudi female carrying a COLQ mutation, microcephaly was reported." (PMID 30808424, 2019).
synaptic congenital myasthenic syndrome (1 paper, 2024). The congenital myasthenic syndromes (CMS) are a diverse group of disorders that have an underlying defect in the transmission of signals from nerve cells to muscles. "Mutations in the collagen-like tail subunit gene (COLQ) of acetylcholinesterase are responsible for recessive forms of synaptic congenital myasthenic syndromes with end plate acetylcholinesterase deficiency." (PMID 38475910, 2024).
tumor (4 papers, 2012 to 2024). "In addition, it was found that there was a statistically significant difference in the expression of nearly all FARG signature-related genes between different neoplasm disease stages, except COLQ (p < 0.05)." (PMID 35958598, 2022).
COLQ also shares sentences with these, for which no sentence is quoted: cancer (2 papers); infection (2); ophthalmoplegia (2); respiratory failure (2); breast adenocarcinoma (1); Burkitt lymphoma (1); channelopathies (1); Crohn disease (1); Duchenne muscular dystrophy (1); heart failure (1); inflammatory bowel disease (1); kidney adenocarcinoma (1); latent infection (1); myotonic dystrophies (1); thymoma (1); type 2 diabetes mellitus (1); ulcerative colitis (1); viral infection (1); weakness (1).